AQP1 (aquaporin 1 (Colton blood group))
Diseases named in the same sentence as AQP1 in open-access papers (continued):
Sharing a sentence is not in itself a finding about the gene and the disease.
Facial palsy (1 paper, 2020). Facial nerve palsy is a dysfunction of cranial nerve VII (the facial nerve) that results in inability to control facial muscles on the affected side with weakness of the muscles of facial expression and eye closure. "In mice with facial palsy caused by HSV-1, AQP1 protein levels increased significantly from day 9 to day 16 after inoculation of HSV-1." (PMID 30923934, 2020). "The upregulation of AQP1 is closely related to intratemporal facial nerve edema in the facial nerve canal, and is also consistent with the symptoms of facial palsy in mice." (PMID 30923934, 2020). "Combined with the upregulation of phosphorylated ERK in mice with facial palsy induced by HSV-1, it could be speculated that the ERK MAPK pathway might also be involved in the increase of AQP1 in the BP mouse model." (PMID 30923934, 2020).
fatal familial insomnia (1 paper, 2019). Fatal familial insomnia (FFI) is a very rare form of prion disease characterized by subacute onset of insomnia showing as a reduced overall sleep time, autonomic dysfunction, and motor disturbances. "The AQP1 levels also increased in the cortex regions of some human prion diseases, including the patients with sporadic Creutzfeldt-Jakob disease (CJD), fatal familial insomnia (FFI) and G114V genetic CJD (gCJD)." (PMID 31814527, 2019).
Fuchs’ dystrophy (1 paper, 2024). "AQP1 has been shown to be downregulated in Fuchs’ dystrophy and PBK/ABK corneas, which is in line with the findings of Verkman and colleagues that AQP1 knockout reduces corneal fluid elimination." (PMID 38612559, 2024).
glomerular diseases (1 paper, 2015). "Unfortunately, there have been no reports about AQP1 alteration related to glomerular diseases in rats." (PMID 25815318, 2015).
glomerulosclerosis (1 paper, 2021). A hardening of the kidney glomerulus caused by scarring of the blood vessels. "p16 staining in both the AQP1+ and AQP1− cell populations in the renal cortex was significantly correlated with percent global glomerulosclerosis and cortical inflammatory infiltrate and fibrosis scores." (PMID 34941841, 2021).
Heat Stroke (1 paper, 2024). A condition caused by the failure of body to dissipate heat in an excessively hot environment or during PHYSICAL EXERTION in a hot environment. "However, the role of AQP1 in heat stroke has not yet been determined." (PMID 39335570, 2024). "However, the role of AQP1 in heat stroke has not yet been elucidated." (PMID 39335570, 2024).
hemorrhage (1 paper, 2025). Loss of blood from the vascular compartment to the exterior or into nonvascular body space as a result of rupture or severance of the blood vessels. "Administering TNF-α and NF-κB inhibitors every 8 hours after IVH (up to 48 hours post-hemorrhage) resulted in reduced CSF production and ventricular enlargement, and decreased NF-κB and AQP1 expression in CPEs compared to the IVH group." (PMID 41270129, 2025).
hemorrhagic stroke (1 paper, 2020). A stroke caused by a bleed on the brain. "It has been reported that AQP1 expression is also involved in cerebral edema formation in hemorrhagic stroke." (PMID 32252790, 2020).
Hepatitis (1 paper, 2024). Inflammation of the liver. "However, no studies have suggested a role for AQP1 in hepatic damage after heatstroke, although a role for AQP1 in hepatic damage has been suggested in hepatitis models." (PMID 39335570, 2024).
hereditary spherocytosis (1 paper, 2021). Hereditary spherocytosis is a congenital hemolytic anemia with a wide clinical spectrum (from symptom-free carriers to severe hemolysis) characterized by anemia, variable jaundice, splenomegaly and cholelithiasis. "Decreased AQP1 expression on the erythrocyte membranes was observed in patients with hereditary spherocytosis and was correlated with the severity of the disease." (PMID 33957977, 2021).
Horseshoe kidney (1 paper, 2025). A connection of the right and left kidney by an isthmus of functioning renal parenchyma or fibrous tissue that crosses the midline. "The primary objective of the present study is to investigate the spatial and temporal expression pattern of KLK6, as well as AQP1 and AQP2, in the cortex of the kidney throughout normal human nephrogenesis and CAKUT: duplex kidneys, horseshoe kidneys, and dysplastic kidneys." (PMID 40428321, 2025). "The primary objective of the present study is to investigate the spatio-temporal expression patterns of KLK6, AQP1, and AQP2 throughout normal human nephrogenesis and congenital kidney and urinary tract (CAKUT) abnormalities: duplex kidneys, horseshoe kidneys, and dysplastic kidneys." (PMID 40428321, 2025).
Hypernatremia (1 paper, 2023). An abnormally increased sodium concentration in the blood. "Acute hypernatremia and hyponatremia promoted the low and high expression of AQP-1, respectively." (PMID 37990154, 2023).
Hypoglycemia (1 paper, 2026). A decreased concentration of glucose in the blood. "In a rat model of lipopolysaccharide (LPS)-induced AKI, both HIF-1α and aquaporin-1 (AQP1) were significantly upregulated within 12 h, concomitant with hypoglycemia, enhanced glycolysis, and a pro-inflammatory shift (elevated IL-6/TNF-α and reduced IL-10)." (PMID 41602837, 2026).
intervertebral disc degeneration (1 paper, 2015). "Objectives of this study were to investigate whether AQP1 and AQP5 expression is altered during intervertebral disc degeneration and if hypoxia and HIF-1 regulate their expression in NP cells." (PMID 25844601, 2015).
intracerebral hemorrhage (1 paper, 2017). A cerebrovascular disorder characterized by bleeding into one or both cerebral hemispheres including the basal ganglia and the cerebral cortex. "In mice with intracerebral hemorrhage, CURC dose-dependently decreased AQP4 and AQP9, but not AQP1 expression, through the NF-κB signaling pathway." (PMID 29292793, 2017).
kidney (1 paper, 2021). "So far, we have shown that the release of AQP1‐ and AQP2‐bearing uEVs (uEV‐AQP1 and ‐AQP2) are altered in experimental kidney injury models such as gentamicin, cisplatin, puromycin aminonucleoside, and ischemia/reperfusion (I/R) models." (PMID 34435473, 2021).
laryngeal carcinoma (1 paper, 2024). Carcinoma that arises from the laryngeal epithelium. "Serum COX-2, AQP1, PGI and G17 levels of different pathological features in patients with laryngeal cancer." (PMID 39634909, 2024). "Correlation analysis of serum COX-2, AQP1, PGI and G17 levels with different pathological features of patients with laryngeal cancer." (PMID 39634909, 2024). "Serum COX-2, AQP1, PGI and G17 levels and ROC analysis of combined prediction of laryngeal cancer." (PMID 39634909, 2024).
leishmaniasis (1 paper, 2024). Infectious disease that is transmitted through the bite of hematophagous female phlebotomine sand flies. "Of all the genes identified in this study, AQP1 was the most extensively studied gene in relation to drug resistance in leishmaniasis." (PMID 39230137, 2024). "Additionally, AQP1 is involved in the transport of various metabolites, including pentavalent antimonial, an important drug for the treatment of leishmaniasis." (PMID 39230137, 2024).
leprosy (1 paper, 2018). Leprosy is a chronic infectious disease affecting primarily the skin and peripheral nervous system. "Additionally, AQP1 may also be involved in skin dryness and loss of elasticity, which are well known signs of leprosy but with unrecognized physiopathology." (PMID 29593724, 2018). "Altered AQP1 expression may improve our comprehension of some well-known clinical issues related to leprosy, such as the dryness found in skin lesions." (PMID 29593724, 2018).
Lewis lung carcinoma (1 paper, 2018). "Acetazolamide inhibited angiogenesis in a chick chorioallantoic membrane assay, and tumor growth and metastasis in mice with Lewis lung carcinoma, perhaps as a result of reduced AQP1 expression." (PMID 29922644, 2018). "Topiramate reduces Lewis lung carcinoma growth and metastasis, with effects similarly attributed to suppression of AQP1 expression." (PMID 29922644, 2018).
liver cirrhosis (1 paper, 2025). "In liver cirrhosis, Piezo1 activation in endothelial cells may lead to ascites by increasing AQP1 expression, a protein that helps water move across cell membranes." (PMID 41034523, 2025).
lymphoma (1 paper, 2022). A malignant (clonal) proliferation of B- lymphocytes or T- lymphocytes which involves the lymph nodes, bone marrow and/or extranodal sites. "On the other hand, in samples below PLA2G2A and RBM47, the expression cut-off, the expression of AQP1 (calculated cut-off: 30 counts, p = 0.026) divided them into the two separate subgroups comprising lymphomas and mild NSOI, respectively." (PMID 35955742, 2022).
male reproductive system disorder (1 paper, 2020). A disease involving the male reproductive system. "The dysregulation or knockdown of AQP1 might lead to male reproductive system disorders." (PMID 32542408, 2020).
metastatic disease (1 paper, 2016). "The inhibition of AQP1 clinically may slow down the progression of CRC, increasing the window for optimal treatment resulting in better survival outcomes, particularly in early stage cases where micro-metastatic disease is present." (PMID 26912239, 2016).
migraine (1 paper, 2010). "This review outlines newly emerging evidence indicating that AQP-1 plays an important role in pain signal transduction and migraine and could therefore serve as a potential therapeutic target for these diseases." (PMID 20969805, 2010). "Indeed, in wild type mice, epidural KCl evoked repetitive CSDs induced up-regulation of AQP-1 expression at both mRNA and protein levels in upper cervical dorsal horn, a key component in the migraine pathway." (PMID 20969805, 2010). "Given that migraine represents a chronic neurological disease, we hypothesized that in a model of migraine AQP-1 expression would be elevated." (PMID 20969805, 2010). "In addition, silencing the mouse AQP-1 gene in vivo using a viral RNA interference approach abolished the elevated avoidance to light of migraine model, which models the photophobia often observed in patients with migraine (data not shown)." (PMID 20969805, 2010).
nasal polyp (1 paper, 2021). "Increased expression of AQP-1 was previously found in nasal polyp tissue, specifically in fibroblasts of the subepithelial area and the periphery of the seromucous glands, and in endothelial cells of venules." (PMID 34206882, 2021).
nonobstructive hydrocephalus (1 paper, 2016). "While much of this effect was due to decreased central venous pressure due to effects of AQP1 deficiency in the kidney, the results suggest reducing AQP1 function decreases both production of CSF and development of nonobstructive hydrocephalus." (PMID 28036023, 2016).
osteoporosis (1 paper, 2015). A condition of reduced bone mass, with decreased cortical thickness and a decrease in the number and size of the trabeculae of cancellous bone (but normal chemical composition), resulting in increased fracture incidence. "For example, they could find direct relevance in osteoporosis based on the observations that Si interferes with aluminium deposition at the bone mineralization front, that bone turnover cells express certain AQGPs and that bone metabolism is impaired in AQP1−/− and AQP9−/− mice." (PMID 26313002, 2015).
otitis media with effusion (1 paper, 2013). Otitis media associated with accumulation of fluid in the middle ear. "The aim of this study was to explore the pathological changes in water homeostasis and the effects of glucocorticoids on aquaporin-1 (AQP1) in guinea pigs with otitis media with effusion (OME)." (PMID 23837036, 2013).
Palmoplantar keratoderma (1 paper, 2023). Abnormal thickening of the skin of the palms of the hands and the soles of the feet. "These diseases include cataract (AQP0), autosomal recessive nephrogenic diabetes insipidus (AQP1 and AQP2) and palmoplantar keratoderma (AQP5) and diminished glycerol release (AQP7)." (PMID 36913438, 2023).
parasitemia (1 paper, 2017). "We find that aqp1-2-3 null T. b. brucei establish parasitemia in mice." (PMID 28358927, 2017).
periodontitis (1 paper, 2020). An acute or chronic inflammatory process that affects the tissues that surround and support the teeth. "Therefore, we investigated the associations between periodontitis, arthritis, and TMDs and SNPs in the aquaporin locus at 12q13.12 and AQP1." (PMID 32130259, 2020). "Furthermore, AQP1 expression is increased in gingival tissues of individuals who have periodontitis, and expression decreases in healed periodontal mucosa." (PMID 32130259, 2020).
prion disease (1 paper, 2019). A transmissible disease that is caused by a protein that is able to induce abnormal folding of normal cellular proteins, leading to characteristic spongiform brain changes, which are associated with neuronal loss without an inflammatory response. "Futhermore, the levels of AQP1 in the brains of human prion diseases were evaluated." (PMID 31814527, 2019). "Abnormal increases of AQP1 and AQP4 in the brains of different prion diseases have also described, e.g., the patients of CJD and BSE-infected transgenic mice." (PMID 31814527, 2019).
radiation proctitis (1 paper, 2020). "We examined the expression of AQP1 and VEGF in rectal tissues of radiation proctitis mice by immunohistochemistry and western blot, and found that there was a positive correlation between them." (PMID 32638843, 2020).
rectal cancer (1 paper, 2020). A primary or metastatic malignant neoplasm that affects the rectum. "Ultra-high b-value DWI may provide an alternative form of non-invasive imaging marker of AQP1 expression in rectal cancer." (PMID 32576929, 2020). "Histogram analysis showed that the ADCaqp value derived from ultra-high b-value DWI of rectal cancer could reflect AQP1’s expression and rectal cancer’s malignancy degree." (PMID 32576929, 2020). "However, neither AQP3 nor AQP5 were correlated with ADCaqp value, which may indicate that AQP1 is mainly responsible for water transport through membranes in rectal cancer." (PMID 32576929, 2020). "In conclusion, the mean, 75th percentile and 97.5th percentile of ADCaqp value derived from ultra-high b-value DWI could reflect AQP1’s expression and the malignancy degree of rectal cancer based on histogram analysis, and the 75th percentile and 97.5th percentile performed better." (PMID 32576929, 2020).
Renal artery stenosis (1 paper, 2024). The presence of stenosis of the renal artery. "Similarly, another study reported ADCuh was positively correlated with AQP1 and AQP2 expression in a rabbit model of renal artery stenosis." (PMID 38943548, 2024).
retinal degeneration (1 paper, 2014). Degeneration of the retina. "Along with the retinal degeneration in transgenic rats, AQP1 labeling of photoreceptor cells decreased, whereas AQP1 immunoreactivity emerged in the inner retinal tissue, in particular within the nerve fiber and ganglion cell layers and around large vessels." (PMID 23755094, 2014). "The labeling of AQP1-positive amacrine cells apparently did not alter in the course of retinal degeneration in transgenic rats." (PMID 23755094, 2014).
scleroderma (1 paper, 2022). Scleroderma is a rare autoimmune connective tissue disorder characterized by abnormal hardening of the skin and, sometimes, other organs. "Our results add additional evidence of the association of AQP1 variants with the development of PAH, not only with idiopathic and hereditary forms, but also in an associated form, such as scleroderma." (PMID 35627312, 2022). "The identification of the AQP1 variant in PAH-SSc suggests that the presence of pathogenic variants in AQP1 may be involved not only in the development of primary forms of PAH, such as idiopathic or hereditary forms, but also in other associated forms such as PAH associated with scleroderma." (PMID 35627312, 2022).
scrapie (1 paper, 2019). A fatal disease of the nervous system in sheep and goats, characterized by pruritus, debility, and locomotor incoordination. "Confocal microscopy revealed notably stronger signals of both AQP1 (red) and PrP (green) in the preparations of scrapie experimental mice than that of normal control." (PMID 31814527, 2019). "We noticed remarkable enhanced expressions of AQP1, AQP4 and AQP9 in the brains of scrapie-infected animals at the terminal stage." (PMID 31814527, 2019). "Western blots revealed markedly increased levels of AQP1, AQP4 and AQP9 in the brain tissues of all tested scrapie-infected mice collected at terminal stage." (PMID 31814527, 2019). "In this study using different methodologies, we have demonstrated the overexpressions of AQP1, AQP4 and AQP9 in the brains of several models of scrapie-infected mice during incubation times and at the terminal stage." (PMID 31814527, 2019). "The assays of the double-stained IFA with AQP1 antibody together with GFAP antibody showed a large amount of colocalization of AQP1 singals (red) with GFAP-positive cells (green), particularly in the brain slices of scrapie-infected mice." (PMID 31814527, 2019).
sporadic CJD (1 paper, 2019). "Increases of AQP1 were also observed in the postmortem brains of the patients with sporadic CJD (sCJD), FFI and G114V genetic CJD (gCJD)." (PMID 31814527, 2019).
Stroke (1 paper, 2018). Sudden impairment of blood flow to a part of the brain due to occlusion or rupture of an artery to the brain. "Second, our data reveal that deletion of AQP1 does not affect platelet functions that are targets for current antiplatelet therapies in stroke and cardiovascular disease (CVD) management." (PMID 29769447, 2018).
systemic inflammatory response syndrome (1 paper, 2024). SIRS is a serious condition related to systemic inflammation, organ dysfunction, and organ failure.
systemic sclerosis (1 paper, 2024). A chronic disorder, possibly autoimmune, marked by excessive production of collagen which results in hardening and thickening of body tissues. "AQP1 has been shown to increase in dermal fibroblasts from patients with systemic sclerosis, probably contributing to tissue fibrosis and edema." (PMID 39335645, 2024).
thyroid cancer (1 paper, 2020). "In thyroid cancer, it is reported that miR-223 inhibits cell proliferation and induces apoptosis by regulating AQP1 expression." (PMID 32903818, 2020).
tick-borne diseases (1 paper, 2015). "Therefore, the authors concluded that I. ricinus AQP1 is not a suitable target to control tick infestation or block transmission of tick-borne diseases." (PMID 26626727, 2015).
toxocariasis (1 paper, 2019). A parasitic infection caused by worms found in domestic animals. "Here, we found that the silenced (partially) Tc-aqp-1 compromised the nematocidal activity of albendazole (a broad-spectrum anthelmintic commonly used for the treatment of toxocariasis), suggesting that TcAQP1 might play a role in the uptake of this anthelmintic." (PMID 31101125, 2019).
viral pneumonia (1 paper, 2020). Inflammation of the lung parenchyma that is caused by a viral infection. "Decrease the level of serum IL-4 and expression of H1N1 mRNA and Aquaporin 1 (AQP1) protein in mice model with viral pneumonia." (PMID 33192523, 2020).